ALB (albumin)
Diseases named in the same sentence as ALB in open-access papers (continued):
Sharing a sentence is not in itself a finding about the gene and the disease.
Lymphadenopathy (7 papers, 2013 to 2025). Enlargement (swelling) of a lymph node. "However, only low pretreatment albumin level and para-aortic lymph node enlargement independently affected overall survival on multivariable analyses (P = .038 and .010, respectively)." (PMID 30085892, 2018). "Albumin/AlbiCpG nanocomplexes upregulated the expression of costimulatory factor CD80 on DCs in draining LNs of C57BL/6 mice, despite accompanying lymphadenopathy." (PMID 29203865, 2017). "Likewise, iFLC and/or summated sFLC above 60 correlated with β2-microglobulin, serum albumin, negatively with hemoglobin, white blood cell and lymphocyte counts, abnormal LDH, Rai and Binet stage, and with the presence of lymphadenopathy and beta-symptoms." (PMID 24288537, 2013).
measles (7 papers, 2009 to 2021). A highly contagious viral infection caused by the measles virus. "The only difference between M-M-R II and M-M-RvaxPro resides in the replacement of human serum albumin in M-M-R II with recombinant human albumin during the manufacturing of measles, mumps and rubella viral bulks." (PMID 19366435, 2009). "One combined measles-mumps-rubella (MMR) vaccine without Human Serum Albumin (HSA) is currently licensed in the USA (M-M-R II; Merck, USA) and another has been developed (PriorixTM [MMR-RIT, GSK, Belgium])." (PMID 28481690, 2017). "A notable finding was that there was also a transient increase in total IgG titers and measles antibody from prior vaccination in the BAL at day 2, yet albumin levels were not increased." (PMID 33688652, 2021).
mental disorder (7 papers, 2017 to 2025). A disease that has its basis in the disruption of mental process. "Male sex (Dep: OR 0.2; Anx: OR 0.3), albumin (Dep: OR 0.1; Anx: OR 0.2) and calcium serum levels (Dep: OR 0.5; Anx: OR 0.4) were significantly associated to the presence of these mental disorders (all variables described presented p-values < 0.01)." (PMID 33805492, 2021). "Multivariate logistic regression analysis showed that the number of clinical symptoms, mental behavior disorder, central hypoventilation, maximum mRS score, and albumin level was independently associated with non-response to short-term first-line treatment." (PMID 35493830, 2022). "Furthermore, ALB, which plays a role in the inflammation and the immune system, has also been demonstrated to be involved in the pathogenesis of mental disorders." (PMID 36419979, 2022). "Patients with a bad outcome versus those with good outcome had significantly higher values in SBP, Mental behavior disorder, GCS, image, NEUT, ALB, FA, BUN, Na, Ca, D-dimer (p < 0.05)." (PMID 39350971, 2024).
metastatic melanoma (7 papers, 2017 to 2025). A melanoma that has spread from its primary site to another anatomic site. "Another study comparing several laboratory and clinical factors in metastatic melanoma reported that albumin was an independent predictor for immunotherapy response after adjustment for LDH, CRP, NLR, brain metastasis, sex, and age41,42." (PMID 38755213, 2024). "Ours is the first study to our knowledge to suggest an independent correlation between normal albumin and long-term survival in metastatic melanoma." (PMID 36290885, 2022). "In a phase III trial, Nab-paclitaxel, an albumin-bound paclitaxel, showed significantly increased progression-free survival in metastatic melanoma patients when compared to dacarbazine alone." (PMID 31979325, 2020). "We then investigated whether serum albumin was an independent predictor from other established biomarkers and clinical factors for the identification of resistance to ICI in patients with metastatic melanoma." (PMID 38755213, 2024).
myasthenia gravis (7 papers, 2016 to 2025). Myasthenia gravis (MG) is a rare, clinically heterogeneous, autoimmune disorder of the neuromuscular junction characterized by fatigable weakness of voluntary muscles. "The contraindications to Botulin A toxin are hypersensitivity to albumin, myasthenia gravis, or Eaton–Lambert syndrome." (PMID 38792665, 2024). "A study conducted by Jeffrey T. and his team involved a retrospective analysis of patients with myasthenia gravis who underwent intravenous plasma exchange with 5% human albumin solution from 2005 to 2010." (PMID 38292942, 2024). "Low ALB levels have also been found in some neural autoimmune diseases such as Guillain–Barre syndrome and Myasthenia Gravis." (PMID 37821922, 2023). "Low ALB levels were also observed in some autoimmune diseases of the nervous system, such as Guillain–Barre syndrome, myasthenia gravis, and NMOSD." (PMID 37153679, 2023).
nasal polyps (7 papers, 2022 to 2025). "Previous research on the sinonasal epithelium has identified differences in aquaporin types between diseased and healthy individuals and lower serum albumin concentrations in patients with nasal polyps." (PMID 40092017, 2025). "Chronic rhinosinusitis with nasal polyps (CRSwNP) is characterized by stromal edema, albumin deposition, and pseudocyst formation." (PMID 40894073, 2025). "Lower levels of serum albumin can be seen in patients with chronic rhinosinusitis with nasal polyposis." (PMID 36923165, 2023). "We selected blood metrics (AUC > 0.7) to investigate their prognostic value based on the comparison of NPC and nasal polyps, including ALB, lymphocyte number, INR, PNI, SII, LMR, NLR, PLR, and WLR." (PMID 37699964, 2023). "With this, we can, with all the cautions, take some notes about the role of serum albumin levels in the pathogenesis of nasal polyposis and not only in chronic rhinosinusitis per se." (PMID 36923165, 2023). "The group of patients with rhinosinusitis and nasal polyposis consisted of 60 patients with a serum albumin value of 4.49 ± 0.29 g/dL, whereas in the control group, the serum albumin value was 4.67 ± 0.2 g/dL." (PMID 36923165, 2023). "Chronic rhinosinusitis with nasal polyps (CRSwNP) is a subtype of chronic rhinosinusitis characterized by high edema in the stroma, albumin deposition, and formation of pseudocysts." (PMID 35378904, 2022). "Edematous stromal tissue and the formation of pseudocysts are common features of nasal polyposis, and it has been suggested that the retention of plasma proteins, such as albumin, may contribute to its growth." (PMID 36923165, 2023). "Recently, some insight has been given into the mechanisms that may drive the formation of nasal polyposis and implies some role for serum proteins, in which we include albumin." (PMID 36923165, 2023). "The ALB concentration in NPC is significantly lower than that in healthy populations and nasal polyps." (PMID 37699964, 2023). "ECRSwNP has shown higher albumin levels in nasal polyps compared to non-eosinophilic CRSwNP." (PMID 40286593, 2025).
obstructive sleep apnea (7 papers, 2022 to 2025). "This study investigates the link between tear lactoferrin, lysozyme, albumin levels and obstructive sleep apnea syndrome." (PMID 40547925, 2025).
peritoneal carcinoma (7 papers, 2010 to 2025). A peritoneum cancer that is located in the inside of the abdomen. "Univariate analysis indicated that gender, weight loss, prior surgical score (PSS), red blood cell, albumin, peritoneal cancer index (PCI), completeness of cytoreduction (CCR), and hyperthermic intraperitoneal chemotherapy (HIPEC) were related to prognosis." (PMID 35739171, 2022). "In addition, some variables, such as preoperative frailty index, albumin level, intraoperative peritoneal carcinoma index, and ERAS compliance, which are known to influence outcome, were not available in the study database and, therefore, not included in our analysis." (PMID 36077721, 2022).
pneumothorax (7 papers, 2004 to 2024). Abnormal presence of air in the pleural cavity. "The need for mechanical ventilation, development of a pneumothorax, and low serum albumin were independent predictors of increased mortality." (PMID 18796158, 2008). "Certain clinical factors such as low serum albumin, need for mechanical ventilation, and development of a pneumothorax were predictive of mortality." (PMID 18796158, 2008).
polycystic ovary syndrome (7 papers, 2012 to 2025). A disorder that manifests as multiple cysts on the ovaries. "Multiple linear regression analysis showed that polycystic ovary syndrome (PCOS), hemoglobin, platelets, albumin, and Fib were significantly associated with the recovery time of patients with OHSS (p = 0.023, p < 0.001, p = 0.007, p < 0.001, and p = 0.019, respectively)." (PMID 35784536, 2022). "Curiously, the in vivo treatment with AGE-albumin did not alter GRP94; however, in lead- and polycystic ovary syndrome-induced UPR, the GRP78 increase was reported to be more significant than the GRP94 increase." (PMID 29802324, 2018).
renal tubular disease (7 papers, 2011 to 2024). "Biomarkers of renal tubular dysfunction such as urinary beta-2-microglobulin or N-acetyl-beta-D-glucosaminidase and of glomerular kidney dysfunction (urinary albumin) were found to be associated with Cd exposure." (PMID 21726464, 2011). "Previous studies have revealed that existence of renal tubular damage even when the urinary albumin excretion rate of diabetic patients is normal, indicating that renal tubular disease may play an important role in the occurrence of DKD." (PMID 35733856, 2022).
T-cell lymphoma (7 papers, 2014 to 2023). "The HGB and ALB levels were lower in T-cell lymphoma and were relatively higher in patients with FL." (PMID 37397371, 2023). "T-cell NHL (HR 3.90, p = 0.017), hemoglobin (HR 0.82 per g/dL, p = 0.017), albumin (HR 0.57 per g/dL, p = 0.019), and IPI (HR 2.02 per unit, p<0.001) were associated with mortality." (PMID 26934054, 2016). "In unadjusted analyses, T-cell NHL (HR 3.90, p = 0.017), hemoglobin (HR 0.82 per g/dL increase, p = 0.017), albumin (HR 0.57 per g/dL increase, p = 0.019), and IPI (HR 2.02 per unit increase, p<0.001) were associated with mortality." (PMID 26934054, 2016). "Differentiating power of cut-off values for pretreatment albumin to globulin ratio on overall survival of patients with NK/T-cell lymphoma." (PMID 26966671, 2016). "In T-cell lymphomas, lower albumin level may reflect cytokine-induced suppression of albumin synthesis and increasing degradation." (PMID 31978091, 2020). "Among these high-grade B-cell and T-cell lymphoma patients, five independent risk factors for CNS relapse were identified: elevated LDH level, serum ALB <35 g/L, <60 years of age, retroperitoneal lymph node involvement, and involvement of more than one extranodal site." (PMID 27624700, 2016). "In addition, T-cell lymphoma was associated with decreased levels of HGB and ALB (P < 0.01)." (PMID 37397371, 2023). "Interestingly, patients with shown factors such as T-cell lymphoma, stages III-IV, “B” symptoms and ulcerative type were often accompanied by abnormal levels of LDH, ADA, HGB and ALB." (PMID 37397371, 2023).
toxicity (7 papers, 2012 to 2023). The degree to which an agent can damage an organism. "The rats treated with chitosan had reduced levels of serum liver marker enzymes and increased activity of antioxidant parameters and of serum albumin in animals with diethylnitrosamine-induced liver toxicity." (PMID 35744025, 2022). "Serum liver biomarkers (ALP, ALT, AST, GGT, bilirubin, total protein, and albumin) are important criteria for the evaluation of liver toxicity." (PMID 22649470, 2012). "In order to assess the level of liver toxicity in the study participants, the activity of ALAT/ASAT, levels of serum albumin, and total bilirubin were measured at baseline and at 12 months and comparisons between these two time points were made." (PMID 34449737, 2021).
uveitis (7 papers, 2019 to 2025). An inflammatory process affecting a part of or the entire uvea. "Their results indicated a significant positive correlation of NAR with clinical and laboratory parameters of BD activity (active uveitis, arthralgia, and oral ulceration), as well as with parameters CRP, ESR, and CRP/albumin ratio (CAR)." (PMID 41230322, 2025). "When statistical comparisons were made between the findings of BD and albumin, CRP and CAR levels, the presence of papulopustular lesion, the presence of uveitis and uveitis activity, and the elevation of CRP and CAR levels were statistically significantly higher (p < 0.05)." (PMID 39050391, 2024).
vitamin B12 deficiency (7 papers, 2014 to 2025). A disease characterized by low serum levels of vitamin B12, either inherited or acquired. "Hypocobalaminemia is associated with lower serum albumin concentration in the case of a gastrointestinal protein loss due to chronic intestinal inflammation." (PMID 32674496, 2020). "Participants with vitamin B12 deficiency had significantly higher levels of IFA, GPA, TNF-α, TC, LDL and albumin compared to those with normal vitamin B12 levels (p < 0.05)." (PMID 33784336, 2021).
Wilson disease (7 papers, 2006 to 2025). A very rare inherited multisystemic disease presenting non-specific neurological, hepatic, psychiatric or osseo-muscular manifestations due to excessive copper deposition in the body. "Patients with Wilson disease are well-treated first-line with copper chelators like D-penicillamine that facilitate the removal of circulating copper bound to albumin and increase in urinary copper excretion." (PMID 38731973, 2024). "Patients with Wilson disease are well treated first line with copper chelators like D-penicillamine that helps remove circulating copper bound to albumin, which facilitates urinary copper excretion via the kidneys." (PMID 38731973, 2024). "ALT, AST, AKP, ALB, UA, Ca, and P are independent predictors of Wilson's disease, and can be used as early predictors." (PMID 36684333, 2022). "Apart from one episode of acute hepatic decompensation, during which transfusion, albumin supplementation and diuretic treatment was necessary, Wilson’s disease manifested as chronic impairment of liver function." (PMID 35578211, 2022). "Circulating copper is normally loosely bound and transported by albumin, constituting the free copper in healthy subjects that is greatly elevated in patients with fulminant liver failure due to Wilson's disease." (PMID 25276143, 2014). "Wilson’s disease decreases serum albumin as a function of liver damage induced by excess liver Cu." (PMID 40628646, 2025). "Alanine aminotransferase (ALT), aspartate aminotransferase (AST), alkaline phosphatase (AKP), albumin (ALB), uric acid (UA), serum calcium (Ca), serum phosphorus (P), and hemoglobin (HGB) are closely related to the occurrence of Wilson's disease (p < 0.1)." (PMID 36684333, 2022). "The prediction model of Wilson's disease contains seven independent predictors: ALT, AST, AKP, ALB, UA, Ca, and P. The AUC value of the prediction model was 0.971, and the C-index value was 0.972." (PMID 36684333, 2022).
allergic rhinitis (6 papers, 2015 to 2023). Inflammation of the nasal mucous membranes caused by an IgE-mediated response to external allergens. "Moreover, LD score regression was significant for the genetic correlation between BMD and height, male-pattern baldness, blood protein levels (albumin), hay fever, and allergic rhinitis." (PMID 32637184, 2020). "In this study, we report the effects and mechanisms of coptisine using monoclonal anti-2,4,6-dinitrophenyl-immunoglobulin (Ig) E/human serum albumin (DNP-IgE/HSA)-stimulated rat basophilic leukemia cells (RBL-2H3 cells) in vitro and an ovalbumin (OVA)-induced allergic rhinitis (AR) in mice." (PMID 30469322, 2018). "Hence, we investigated the anti-allergic action of coptisine on DNP-IgE/HSA-stimulated rat basophilic leukemia cells (RBL-2H3 cells) and ovalbumin (OVA)-induced allergic rhinitis in mice." (PMID 30469322, 2018).
anxiety disorder (6 papers, 2014 to 2025). A category of psychiatric disorders which are characterized by anxious feelings or fear often accompanied by physical symptoms associated with anxiety. "Alkaline phosphatase (AF), albumin (ALB24), creatinine (BKR), eosinophil granulocytes (EO), erythrocytes (ER), and lymphocytes (LY) were found common predictor variables (based on high IncNodePurity value) for all anxiety disorders." (PMID 33970950, 2021).
aortic stenosis (6 papers, 2021 to 2026). Aortic valve stenosis is a aortic valve disease caused by the incomplete opening of the aortic valve. "Background and Objectives: This study investigated the prognostic value of the C-reactive protein-albumin-lymphocyte (CALLY) index in predicting all-cause mortality among patients undergoing transcatheter aortic valve implantation (TAVI) for severe aortic stenosis." (PMID 42075625, 2026). "Age, physical activity, C-reactive protein, and serum albumin levels—but not progressive aortic stenosis—predicted all-cause mortality." (PMID 34513029, 2021).
autonomic neuropathy (6 papers, 2015 to 2025). An inherited or acquired peripheral neuropathy affecting the autonomic nervous system. "Within the population with hATTR‐CA, albumin levels are influenced by the presence of concomitant polyneuropathy, and more specifically autonomic neuropathy, which results in impaired gastrointestinal motility and malabsorption." (PMID 38314569, 2024). "Studies indicate that DN markers including urinary albumin excretion and UACR impairment coexist with autonomic neuropathy and reduced HRV." (PMID 40370786, 2025).
babesiosis (6 papers, 2014 to 2025). Babesiosis refers to a condition caused by microscopic parasites that infect the red blood cells. "Serum biochemistry revealed increase (p<0.01) value of alkaline phosphatase, alanine aminotransferase, aspartate aminotransferase, and globulin as well as decrease in albumin levels (p<0.05) in dogs with babesiosis as compared to healthy dogs." (PMID 29184369, 2017). "All spots, except spot 432, were up-regulated in diseased dogs while the down-regulation of spot 432 resulted from decreased levels of antithrombin III, vitamin D binding protein and albumin in dogs with babesiosis comparing to healthy dogs." (PMID 24885808, 2014).
basophilic leukemia (6 papers, 2015 to 2021). "Kaempferol (10-20 μM) inhibited mast cell degranulation and prostaglandin release, leading to the development of aberrant airways in basophilic leukaemia (RBL-2H3) mast cells obtained from dinitrophenylated bovine serum albumin (DNP-BSA)-sensitised rat." (PMID 33295229, 2020). "To test this, we activated rat basophilic leukemia (RBL-2H3) mast cells with anti-2,4-dinitrophenyl IgE (antibody) and 2,4-dinitrophenyl human serum albumin, which served as an antigen." (PMID 31695078, 2019). "Here, we investigated the effect of the ethanol extract of Boehmeria nivea (BNE) on degranulation rat basophilic leukemia (RBL)-2H3 mast cells stimulated with anti-dinitrophenyl (anti-DNP) and bovine serum albumin (BSA) during immunoglobulin E (IgE)-mediated allergic immune response." (PMID 32932637, 2020).
bladder tumor (6 papers, 2015 to 2022). "Further data are required to suggest a promising role of the fibrinogen-to-albumin ratio as a diagnostic biomarker for bladder tumors." (PMID 36295649, 2022). "This study aimed to investigate the prognostic value of albumin-to-fibrinogen ratio (AFR) for BC patients underwent radical cystectomy (RC) or transurethral resection of bladder tumor (TURBT), and develop predictive nomograms based on AFR." (PMID 34475999, 2021). "In this model, albumin-bound As2O3 appeared to be an effective method for treating bladder tumors, with less severe hematologic side effects compared with As2O3 alone." (PMID 25915411, 2015). "In this experiment, we demonstrated significant shrinkage of bladder tumors in mice through internal iliac arterial infusion of albumin-bound As2O3 with minimal adverse effects." (PMID 25915411, 2015). "Hence, for the analysis of T24 bladder tumor cell proliferation, concentrations of TY = 40 μM and 20 μM were selected, with which complexes with Ag+ (TY-Ag = 1:0.5 molar ratio) and in some experiments additionally with albumin (BSA-TY = 1:10 molar ratio) were prepared." (PMID 35008445, 2021).